CASP1 (caspase 1)
Diseases named in the same sentence as CASP1 in open-access papers (continued):
Sharing a sentence is not in itself a finding about the gene and the disease.
infection (continued). "Casp-1/11 but not RIP3K deficiency significantly reduced the expression of CD127 with an increase of KLRG1 expression on OT-I CD8+ T cells after 7 days of infection." (PMID 32328060, 2020). "Caspase-1 dominates the antimicrobial response to Salmonella at early time points, while caspase-11 mediated defense plays a larger role later in the course of infection." (PMID 32282854, 2020). "Here, we determined whether CASP-1 activation (an essential component of the NLRP3 inflammasome) participates in infection control mediated by eUTP." (PMID 33061823, 2020). "pseudomallei triggers caspase-1 cleavage at 3h post infection." (PMID 33137811, 2020). "The loss of either TLR2 or caspase-1 dramatically attenuated cytokine/chemokine production during S. aureus craniotomy infection, which supports the lack of this positive feedback loop and the inability to contain bacterial growth." (PMID 32290861, 2020). "In addition to non-expression of the inflammasome pathway signaling, L. infantum was also unable to activate caspase-1 and IL-1β production in early and later periods post-infection." (PMID 31961876, 2020). "In addition, caspase-1-mediated cell death is known as pyroptosis in macrophages following infection." (PMID 31727879, 2019). "IL-1β production was dependent on inflammasome activation since Casp1/11 deficient macrophages failed to trigger IL-1β production in response to the infection." (PMID 31211814, 2019). "However, infection in the presence of cathelicidin promotes caspase-1 activation, release of IL-1β and IL-18, and the influx of neutrophils." (PMID 30978238, 2019). "Similarly, T. gondii infected Nlrp3-/-, Asc-/-, and Casp1/11-/- mice demonstrated modest reductions of IFN-γ within the sera on day 8 post-infection." (PMID 31194844, 2019). "Analysis of the parasite burden revealed that while TLR11 was the primary mediator of parasite control at the site of infection, Casp1/11 plays an important role in cooperation with TLR11 in providing systemic Myd88-dependent immunity towards this intracellular pathogen." (PMID 31194844, 2019). "Indeed, caspase-1, activated in response to infection by a macromolecular protein complex termed ‘inflammasome’, is able to cleave pro-IL-1β into its mature form, contributing to host inflammatory response and tissue damage." (PMID 31026281, 2019). "The NLRP3 inflammasome is a multiprotein complex that activates caspase-1 during infection and ROS." (PMID 30779706, 2019). "Immunoblots confirmed the presence of active caspase-1 p20 and proteolytic processing of pro-IL-18 upon infection with wild-type (WT) EPEC but not the T3SS-deficient ΔescF mutant." (PMID 31018119, 2019). "These variants were found in inflammasome genes (NLRP1/3, CASP1), genes mediating inflammasome inactivation via auto and mitophagy (RIPK2, MEFV), and genes involved in response to infection with DNA viruses (POLR3A, DHX58, IFIH1) and to type-1 interferons (TYK2, PTPRC)." (PMID 31235738, 2019). "To further investigate the LRV-inhibition of the NLRP3 inflammasome in human cells, we measured IL-1β and Casp1 p20 in response to L.g.− and L.g.+ infection in cells treated with KCl (which impairs potassium efflux and activation of NLRP3) or Poly:IC (TLR3 agonist)." (PMID 31754185, 2019). "Therefore, GSDMD and multiple caspases (CASP1, CASP7 and CASP8) operate downstream of the NAIP5/NLRC4 inflammasome for restriction of infection by pathogenic bacteria." (PMID 31251782, 2019). "Quantification of the percentage of epithelial cells with lysosomal leakage, demonstrated that this was significantly greater in infected cells exposed to LL-37, when compared to LL-37 alone or PAO1 infection alone, recapitulating the pattern for caspase-1 activation." (PMID 30978238, 2019). "Similarly, active caspase-1, mature IL-1β, and secondsreted IL-1β were induced by infection with either E. coli or P. mirabilis, and this induction was reduced by NLRP3 knockdown." (PMID 30823406, 2019).
infection (continued). "Nevertheless, these unprimed WT macrophages displayed caspase-1 processing starting 12 hours after MNV infection, demonstrating that MNV itself has the capacity to trigger inflammasome activation even in the absence of sufficient amounts of pro-IL-1β that would contribute to inflammatory responses." (PMID 31017981, 2019). "We next used the FLICA Caspase-1 assay to validate the previous western blot results and confirm whether Caspase-1 is more activated in human corneal epithelial following infection with virulent strains and clinical isolate of HSV-1." (PMID 31367214, 2019). "The NLRP3 inflammasome is a multiprotein platform that is activated upon cellular infection or stress and subsequently leads to caspase-1-dependent secretion of proinflammatory cytokines, such as IL-1β and IL-18, and an inflammatory form of cell death termed as pyroptosis." (PMID 31222000, 2019). "Activated NLRP3 by infection or various stress induces apoptosis-associated speck-like protein containing a caspase activation and recruitment domain (CARD) domain (ASC), and then NLRP3 inflammasome is formed in combination with activated caspase-1 precursor." (PMID 31731792, 2019). "Also, because ExoU can inhibit the NLRC4 inflammasome and caspase-1, the level of IL-1β production would be expected to be higher after infection with PAO1 than after infection with PA103." (PMID 30455194, 2019). "Moreover, we demonstrated that HSV-1 virulence promotes Caspase-1 activation in innate immune cells (inflammatory monocytes and neutrophils) infiltrating the corneas following infection with virulent strains of HSV-1." (PMID 31367214, 2019). "The mature caspase 1 proteolytically cleaves cytosolic pro-IL-1β and pro-IL-18, which are then secreted as inflammatory cytokines, which activate the inflammatory arm of the immune response to infection." (PMID 30013955, 2018). "To investigate whether NLRP6 triggers inflammasome activation during S. aureus infection, we infected BMDMs from WT and NLRP6 KO (KO) mice with S. aureus (MOI: 20) and measured the extent of caspase-1 activation at 8 hours post-infection." (PMID 30248149, 2018). "Moreover, in comparison to the infection with wt, χ12253 LPS strain did lead to a lower IL-1β release from cells and decreased the level of caspase-1 cleavage into a mature form." (PMID 30429830, 2018). "Caspase 1 deficiency reduces the survival rate of mice during non-lethal challenge with influenza virus, whereas the caspase-1 deficiency protects mice against lethal infection of the virus." (PMID 30012970, 2018). "We found that IL-1β and IL-18 mRNA, as well as protein levels of mature IL-1β (p17) and cleaved fragment of pro-caspase-1 (p10) were significantly increased at 18 h post infection (p.i.), suggesting that inflammasome signaling was activated at early stage of YM infection." (PMID 30470758, 2018). "In the early stage of in vitro infection of mouse peritoneal macrophages, X4550(pYA3334-P-SspH2-EscI) could significantly (P < 0.05) enhance intracellular caspase-1 activation and pyroptotic cell death of macrophages, when compared with X4550(pYA3334-P-SspH2)." (PMID 29523140, 2018). "After in vitro infection of mouse peritoneal macrophages, flow cytometric assay indicated that all bacteria could induce the activation of intracellular caspase-1 at 1, 3, 5 h post infection (hpi), when compared with the uninfected control (P < 0.05)." (PMID 29523140, 2018). "Accordingly, this decrease might also have induced only a slight upregulation in CASP-1 at 48 hours after infection." (PMID 28873330, 2018). "Taken together, these findings suggest that IL-1β, IL-18, and caspase-1 may have different physiological function in the host response during infection." (PMID 29616195, 2018).
infection (continued). "Treatment with the caspase-1 inhibitor YVAD-CHO in combination with PGE2 abolished release of IL-1β upon infection with both Y. enterocolitica and S. Typhimurium, supporting the fact that caspase-1 is responsible for the PGE2-triggered stimulation of inflammasome." (PMID 30429830, 2018). "In addition, caspase-1 was elevated in two to three folds at both mRNA and protein levels at 6 h post-infection (p.i.), suggesting the activation of caspase-1 was a rapid cellular response to EV71 infection." (PMID 29440739, 2018). "Macrophages were infected with H37Rv in the presence or absence of CA074-Me, a potent inhibitor of CTSB activity and in certain conditions other cathepsins, and mature IL-1β as well as cleaved caspase-1 were measured in supernatants at 6 and 24 h after infection." (PMID 29977244, 2018). "Thus, P. aeruginosa T3SS effector protein ExoU can inhibit activation of the NLRC4 inflammasome and caspase-1 and, as a result, downregulates rapid neutrophil recruitment and rapid infection clearance." (PMID 30276212, 2018). "In medium-dose infection, Casp1−/− and Il1r1−/− mice were partially resistant." (PMID 30470758, 2018). "The expression of caspase-1 mRNA in the kidney showed a “saddle pattern” of change over time post-infection, which was different from that in the other three organs (liver, lung, and testis) and remained higher than that in the blank group at the endpoint of the study (P < 0.05)." (PMID 29490620, 2018). "In addition, not only the production of IL-1β protein but also caspase-1 activation was significantly elevated in the colon tissue of infected mice after infection." (PMID 29616195, 2018). "The mature caspase-1 then proteolytically cleaves cytosolic pro-IL-1β and pro-IL-18, which are subsequently secreted as inflammatory cytokines that activate the inflammatory arm of the immune response to infection." (PMID 30013955, 2018). "Because IL-1β and IL-18 are upregulated by caspase-1, caspase-1 may mediate additional mechanisms such as pyroptosis, which supports the importance of its regulation during infection." (PMID 29616195, 2018). "Mice lacking AIM2, ASC, or caspase-1 are highly susceptible to infection and exhibit an increased bacterial burden compared with wild-type mice." (PMID 29085810, 2017). "Therefore, wild-type and Asc−/− cells mainly differ in the form of active caspase-1 induced by STm infection." (PMID 28147281, 2017). "Therefore, the expression of IL-1β, IL-18, NLRP3, Caspase-1, ASC, and Syk mRNA was characterized in lung macerates of WT, Nlrp3−/−, Casp1/11−/−, and Asc−/− mice at week 4 after infection." (PMID 28740491, 2017). "Indeed, at 10 h post-infection, we observed processing of the apoptotic caspases-8, 9 and 3 in infected Casp1/Casp11-/- BMDMs." (PMID 28968459, 2017). "Interestingly, an increased influx of GR1+Ly6G+ PMN cells was seen in the lungs of WT mice in comparison with Nlrp3−/−, Casp1/11−/−, and Asc−/− mice at 48 h, 2 and 4 weeks of infection." (PMID 28740491, 2017). "It has been demonstrated that infection of monocytes and macrophages by some strains of Chlamydia, including Chlamydia trachomatis, Chlamydia muridarum, and Chlamydia psittaci, leads to IL-1β secretion consequent to the activation of Caspase-1." (PMID 28660207, 2017). "Of notice, prolonged infection with WT P. aeruginosa (6 or 8 h), but not with ΔlasR/rhlR, caused a manifest degradation of caspase-1 and IL-1β in the culture supernatants." (PMID 28396663, 2017). "In addition, previous studies using the Salmonella enterica serovar Typhimurium have indicated that both caspase-8 and caspase-1 are recruited to the ASC puncta in response to infection." (PMID 28771586, 2017). "However, Caiap-deficient larvae showed increased susceptibility to WT ST compared with their control siblings and impaired caspase-1 activity in response to the infection." (PMID 29123523, 2017).
infection (continued). "Our data suggest that caspase-8 activation in the Naip5/NLRC4/ASC inflammasome may favor host responses during infections against pathogens that inhibit components of the pyroptotic cell death including caspase-1 and gasdermin-D." (PMID 28771586, 2017). "We found that whereas C57BL/6 macrophages readily triggered the production of IL-1β after 24 hours of infection with flagellated bacteria, the Casp1/11-/- or Asc/Casp1/11-/—deficient cells do not trigger a IL-1β production." (PMID 28771586, 2017). "In another study using a murine model of systemic PCM induced by intravenous infection, the susceptibility of NLRP3 and caspase-1 knockout mice to P. brasiliensis infection was evaluated and their increased susceptibility was associated with reduced IL-18 production and Th1 immunity." (PMID 28740491, 2017). "Active caspase-1 mediates a series of effector responses required for the control of infections." (PMID 28150715, 2017). "In addition, pharmacological inhibition of caspase-1 impaired the biosynthesis of all eicosanoids in response to ST infection." (PMID 27363812, 2016). "In addition, caspase-1 mRNA and expression of caspase-1 were also enhanced in the macrophages after infection with Ms_PPE32 in comparison with MS_Vec." (PMID 27634911, 2016). "Consistent with the involvement of caspase 1 in IL-1ß secretion induced by this commensal, we found that the infection led to increased levels of the processed p10 form of the enzyme as detected by western blotting (the corresponding uncropped blots are shown in S4 Fig)." (PMID 27505062, 2016). "Moreover, ASC has been demonstrated to change the subcellular localization of Nlrc4 and caspase-1 upon infection via recruitment to discrete puncta structures which is important not for the activation but for the cleavage of caspase-1." (PMID 27148204, 2016). "Caspase-1, -3 and -9 enzymatic activity was increased following the infection." (PMID 27124409, 2016). "Also, liver caspase-1 contents were augmented to a comparable extent during infection in WT and SRBI−/− mice and levels of IL-1β were not significantly changed." (PMID 27694929, 2016). "However, if caspase-1 was pharmacologically inhibited later in infection, bacterial replication was restricted." (PMID 29056735, 2016). "IL18 is a Caspase-1-dependent inflammatory cytokine induced by infection with C. trachomatis." (PMID 26808832, 2016). "More interestingly, forced expression of Gbp4 RNA alone increased resistance to the infection, caspase-1 activity and ST clearance, confirming the specificity of the MO and revealing the crucial role of Gbp4 in the resistance to this infection." (PMID 27363812, 2016). "To further confirm LM mainly activates NLRP3 inflammasome, we used wild-type and NLRP3−/− B6 cells to analyze the IL-1β release and caspase-1 activation upon LM infection (ATP and poly (dA:dT) were used as the NLRP3 and AIM2 inflammasome activators, respectively)." (PMID 26911557, 2016). "Infection with Pg increased significantly the enzymatic activity of caspase-1, -3 and -9." (PMID 27124409, 2016). "This hypothesis came from the observation that the Chlamydia-secreted effector protein, CPAF, prevents pyroptosis by inhibiting ASC and caspase-1 at early time points during infection." (PMID 29056735, 2016). "Differences in the cytokine levels were also evident in the Casp1-/- BMDMs 24 h post-infection." (PMID 26741365, 2016). "Further studies revealed that L. pneumophila causes efficient inflammasome assembly and caspase-1 activation in murine but not human infections." (PMID 27148204, 2016). "However, the expression of cleaved caspase-1 was significantly elevated by D39 infection, and treatment with siAtg5 further increased the expression levels." (PMID 26683708, 2015). "Caspase-1−/− and IL-1β−/−IL-18−/− mice often exhibit similar infection response phenotypes." (PMID 26500655, 2015).
infection (continued). "However, in the late phase of infection, IL-1β secretion and caspase-1-dependent cell death were induced by ROS." (PMID 26683708, 2015). "In addition, caspase-1 activation and subsequent cytokine maturation were significantly inhibited by D39ΔPLY infection." (PMID 26683708, 2015). "In addition, the expression of IL-1β, IL-18 and caspase-1 p10 was gradually increased and remained elevated until 7 h of infection." (PMID 26683708, 2015). "Caspase-1 was activated and cleaved time- and concentration-dependently by D39 infection." (PMID 26683708, 2015). "It further remains unclear whether cleavage by proteases other than caspase-1 can occur during infection, or whether it would promote or inhibit IL-1 signaling." (PMID 26500655, 2015). "Taken together, these data indicate that caspase-11 and caspase-1 play opposing roles in modulating cofilin phosphorylation status during infection, as caspase-11 is required for the phosphorylation of cofilin and caspase-1 is necessary for its dephosphorylation." (PMID 26686473, 2015). "Notably, pre-infection with C. burnetii induced a significantly higher expression of pro-casp-1 and pro-IL-1β, than single infections with L. pneumophila, possibly because of the presence of C. burnetii PAMPs during the 24-h pre-stimulation." (PMID 26687278, 2015). "Thus, at this time, we cannot confirm that abortive infection triggers pyroptosis in the gut and cannot exclude alternative triggers for Caspase-1 activity." (PMID 24495380, 2014). "Moreover the data from our human lung tissue infection model show that NTHi stimulates caspase-1 expression and leads to a strong release of IL-1 family cytokines IL-1β and IL-18." (PMID 23840534, 2013). "The attenuation of the activation by infection with a double mutant of TdhA and S (ΔtdhAS) was observed, but caspase-1 activation and IL-1β processing persisted, suggesting that additional bacterial stimulators are involved in caspase-1 activation." (PMID 23357873, 2013). "Importantly, inflammatory burst induced by S. flexneri, associated with bacterial invasion and dissemination as well as resolution of infection by a competent host, requires caspase-1, IL-1β, and IL-18." (PMID 24324933, 2013). "However, LDH release from NLRC4-deficient cells was considerably decreased by infection with ΔtdhASΔh1, raising the possibility that some effectors encoded in the h1 region affect NLRP3-mediated LDH release in a caspase-1 activation-independent manner." (PMID 23357873, 2013). "In addition, Aim2 and Asc were proposed to trigger caspase-1-independent, caspase-8, -9, -3-mediated apoptosis of macrophages in response to infection with F. tularensis, contributing to restriction of bacterial replication in these cells." (PMID 24324933, 2013). "Thus, depriving a replicative niche to intracellular pathogens through pyroptosis is one critical contribution of caspase-1 during some infections." (PMID 24367258, 2013). "Notably, recognition of TDHs and T3SS-1 were required to induce caspase-1-dependent pyroptosis in response to infection." (PMID 24324933, 2013). "To evaluate the pro-inflammatory responses of NLRP3−/− and caspase-1−/− mice during the acute phase of T. cruzi infection, we assessed the level of cytokines and NO in the supernatants of cultured spleen cells isolated 10 days after infection." (PMID 24098823, 2013). "Infection of NHBE cells by HRV is thus likely associated with recognition of viral products, oligomerisation of the inflammasome resulting in caspase-1 activation and release of mature IL-1β and IL-18, but also an alternative active process resulting in IL-1α release." (PMID 23723976, 2013). "Despite our incomplete understanding of all of these processes, it is clear that integration of inflammatory programs, with caspase-1 as their central regulator, allows a cell to comprehensively react to injury or infection, preventing deleterious delays in initiating immune responses." (PMID 24367258, 2013).